SEMA5A (semaphorin 5A)
Diseases named in the same sentence as SEMA5A in open-access papers (continued):
Sharing a sentence is not in itself a finding about the gene and the disease.
Anxiety (1 paper, 2014). Intense feelings of nervousness, tension, or panic often arise in response to interpersonal stresses. "Sema5A−/− congenic mutants show normal locomotor behavior in the open field test, and mutant and WT mice exhibit similar anxiety levels." (PMID 25313870, 2014). "Although altered social behavior may be secondary to increased anxiety, this appears unlikely since Sema5A−/− mice show no signs of anxiety in the open field test or in the elevated plus maze compared to WT controls." (PMID 25313870, 2014).
autoimmune disease (1 paper, 2017). A disorder resulting from loss of function or tissue destruction of an organ or multiple organs, arising from humoral or cellular immune responses of the individual to their own tissue constituents. "SEMA5A is a secreted semaphorin involved in immune regulation and the pathogenesis of autoimmune diseases." (PMID 28100171, 2017).
breast tumors (1 paper, 2025). "For instance, other known ligands of PLXNB2, such as SEMA5A and SEMA4D, are either not expressed or not detectable in breast tumors at the primary site." (PMID 40818975, 2025).
chronic myeloid leukemia (1 paper, 2018). "Decreased expression of Sema5A was also observed in the BV173 human chronic myeloid leukemia (CML)-lymphoid blast crisis cells transduced with the same c-Myb lentiviral vector, confirming that c-Myb regulates the expression of Sema5A." (PMID 30454024, 2018).
Cirrhosis (1 paper, 2018). A chronic disorder of the liver in which liver tissue becomes scarred and is partially replaced by regenerative nodules and fibrotic tissue resulting in loss of liver function. "Serum concentration of SEMA5A <12ng/mL showed sensitivity of 85.0% and specificity of 63.3% (AUC 0.79) in the detection of cirrhosis." (PMID 30592759, 2018).
cognitive deficits (1 paper, 2024). "In addition, previous studies have revealed that the dysregulation of Sema5a causes aberrant synaptogenesis in the hippocampus and cognitive deficits." (PMID 38750585, 2024).
endothelial dysfunction (1 paper, 2024). In vascular diseases, endothelial dysfunction is a systemic pathological state of the endothelium (the inner lining of blood vessels) and can be broadly defined as an imbalance between vasodilating and vasoconstricting substances produced by (or acting on) the endothelium. "We also found dysregulation of angiogenesis genes (XDH, SEMA5A, and SULF1) and the Rap1 pathway (ADORA2B, GNAO1, SULF1, and EFNA2), which promotes endothelial homeostasis and may be involved in endothelial dysfunction-associated cardiovascular pathologies." (PMID 38255763, 2024).
epilepsy (1 paper, 2019). A brain disorder characterized by episodes of abnormally increased neuronal discharge resulting in transient episodes of sensory or motor neurological dysfunction, or psychic dysfunction. "Additionally, SEMA5A has not been reported to be involved in epilepsy and is absent in any gene database related to epilepsy." (PMID 31354784, 2019).
epilepsy syndrome (1 paper, 2019). A syndrome that has a characteristic cluster of clinical features and/or lectroencephalographic (EEG) findings that reflect underlying epileptic activity. "Furthermore, SEMA5A and its interacting genes were associated with ASD, epilepsy syndrome and developmental disorders of mental health." (PMID 31354784, 2019).
helminth infection (1 paper, 2023). "Moreover, SNPs located in SEMA5A gene have been found to be associated with helminth infection in humans." (PMID 36699132, 2023).
infantile epilepsy (1 paper, 2023). "The genomic region also contains the sema5a gene that is associated with causing infantile epilepsy." (PMID 38133141, 2023).
islet-cell carcinoma (1 paper, 2018). "We also took advantage of KC and KPC mouse models for studying SEMA5A expression in PDAC and RT2 model of islet-cell carcinoma for PanNET." (PMID 29464045, 2018).
liver diseases (1 paper, 2022). "This highlights the possible role of SEMA5A in liver diseases, the mechanism of which is still unknown and should be confirmed in further studies." (PMID 36551769, 2022).
liver fibrosis (1 paper, 2022). "Next, we investigated the genotype frequency and allele distribution of selected SEMA3A, SEMA4A and SEMA5A SNPs and the possible association between the SNPs, NAFLD and liver fibrosis." (PMID 36551769, 2022).
multiple myeloma (1 paper, 2023). "In patients with newly diagnosed multiple myeloma, SNHG18 and its possible target gene SEMA5A are upregulated, and high expression are related to poor prognosis." (PMID 36927398, 2023).
myopia (1 paper, 2019). "Our study identified methylation differences in the semaphorins, such as SEMA3F, SEMA4B, SEMA4C and SEMA5A that were significantly associated with myopia." (PMID 30858441, 2019).
neuroblastoma (1 paper, 2020). Neuroblastoma (NB) is the most common solid, extracranial childhood tumor. "While Pea3 upregulates transcription of Sema3D and represses Sema5B, for example, Erm and Er81 upregulate Sema5A and Er81 regulates Unc5C and Sema4G while repressing EFNB3 in SH-SY5Y neuroblastoma cells." (PMID 33097800, 2020).
oesophageal cancer (1 paper, 2016). "The mutations in ABCB1 and SEMA5A described here have not been previously reported in oesophageal cancer." (PMID 27600491, 2016).
osteoarthritis (1 paper, 2022). A noninflammatory degenerative joint disease occurring chiefly in older persons, characterized by degeneration of the articular cartilage, hypertrophy of bone at the margins and changes in the synovial membrane. "Here, we found that Semaphorin 5A levels were significantly higher in synovial fluid and synovial tissue from RA patients compared with osteoarthritis patients." (PMID 35835748, 2022).
rectal adenocarcinoma (1 paper, 2025). "Our study shows that multiple immune genes associated with ASCC3, including JAK1, NFKB1, SEMA5A, NR2C2, CNTF and CREB1, positively impact the prognosis of rectal adenocarcinoma patients." (PMID 40881169, 2025). "ASCC3 is a specific protective factor for rectal adenocarcinoma across various cancer types, particularly in digestive system cancers, and can synergize with several immune-related genes, including JAK1, NFKB1, SEMA5A, NR2C2, CNTF, and CREB1, to influence patient prognosis." (PMID 40881169, 2025).
rectal cancer (1 paper, 2025). A primary or metastatic malignant neoplasm that affects the rectum. "The combination of ASCC3 with several immune-related genes, including JAK1, NFKB1, SEMA5A, NR2C2, CNTF and CREB1, plays a significant predictive role in the prognosis of rectal cancer patients." (PMID 40881169, 2025). "Additionally, our diagnostic and prognostic models, constructed using machine learning, highlight the significant predictive value of ASCC3 in combination with various immune-related genes, including JAK1, NFKB1, SEMA5A, NR2C2, CNTF and CREB1, for rectal cancer prognosis." (PMID 40881169, 2025).
steatosis (1 paper, 2022). Increased lipid within the cytoplasm of cells. "Third, we found a lower expression of SEMA5A in patients with NAFLD, regardless of the steatosis and fibrosis stage." (PMID 36551769, 2022).
Vestibular schwannoma (1 paper, 2013). A vestibular schwannoma (also known as acoustic neuroma, acoustic neurinoma, or acoustic neurilemoma) is a benign, usually slow-growing tumor that develops from the VIIIth cranial nerve supplying the inner ear. "Our findings also demonstrate that the MET signaling pathway, which is possibly enhanced by the upstream signaling of SPP1, ITGA4/B6, PLEXNB3/SEMA5A and CAV1, appears to play a paramount role in the development and maintenance of vestibular schwannoma." (PMID 23354516, 2013).
tumor (29 papers, 2011 to 2025). "It was suggested by these results that Sema5A was associated with tumor growth, metastatic potential, and invasiveness." (PMID 36713527, 2022). "Semaphorin 5A is a member of the Semaphorin family that has close associations with various pathophysiological phenomena including cell migration, tumor growth, and immune responses." (PMID 35835748, 2022). "A possible explanation for the discrepancy that both gain of SEMA5A in primary tumor cells or loss of SEMA5A in metastatic PC cells result in higher metastasis may come from the involvement of two different pathways." (PMID 30577767, 2018). "Finally the SEMA5A gene on chromosome 5 at position 9190519 carries a mutation in the tumour found in 35% of the WGS reads whilst the MFD-1 parent cell line and clones are homozygotes mutant." (PMID 27600491, 2016). "Given mesenchymal tumor cells are more tumorigenic, motile and hence more metastatic, our experimental observations suggested that there is a possibility that loss of SEMA5A may promote metastasis." (PMID 30577767, 2018). "In our study, we have demonstrated that M2 TAM-derived secreted protein SEMA5A would interact with tumor cell membrane located in PLXNB3 and thus induce tumor cell proliferation for metastatic niche expansion via enhancing the Warburg effects." (PMID 36741230, 2023). "The outgrowth facilitation PLXNB3 exerted on tumor cells was triggered by SEMA5A which was also consolidated by SEMA5A-ΔTSP." (PMID 36741230, 2023). "We aimed to check the relationship of events including the Warburg effect, tumor growth, and SEMA5A overexpression." (PMID 36741230, 2023). "It has been noticed that PLXNB3 were upregulated in most cell lines, indicating the tumor resident behavior of which, while SEMA5A was maintained at a relative low level for its source was usually exogenous." (PMID 36741230, 2023). "In NHPVA ADC, we discovered remarkable involvement of MMP2 in tumor angiogenesis, and the SEMA5A–PLXNB3 interaction was possibly related to neural invasion." (PMID 36725337, 2023). "Altogether, our results have pushed forward evidence that SEMA5A-PLXNB3 axis promotes tumor cell proliferation via enhancing the Warburg effect." (PMID 36741230, 2023). "We also observed that upregulations of the Warburg effect key enzymes PKM2 or PGK1were coexpressed with KI67 in SEMA5A-enriched tumor niches of human PDAC liver metastasis, demonstrating the enhanced proliferation ability in the Warburg effect area." (PMID 36741230, 2023). "It’s well-known that semaphorin 5A (Sema5A) and its receptors play an important role in the invasion and metastasis of tumor cells by promoting angiogenesis." (PMID 35350431, 2022). "RA SFs exhibited tumor-like properties, such as increased proliferation and migration and decreased apoptosis, and Semaphorin 5A significantly promoted these characteristics." (PMID 35835748, 2022). "First, Sema5A induces lymphangiogenesis and the contact between tumor cells and lymphatic endothelial cells." (PMID 33537086, 2021). "In vitro and in vivo experiments with NSCLC cellular models indicated a clear tumor suppressor activity of Sema5A." (PMID 33537086, 2021). "A growing body of evidence suggests that SEMA5A plays an important role in tumor progression through its interaction with plexin-B3." (PMID 29977159, 2018). "SEMA5A protein expression was significantly higher in tumor tissues from stage IIb patients than in tumors tissues from stage Ia, Ib, and IIa patients (P < 0.05)." (PMID 29977159, 2018). "First, SEMA5A induces lymphangiogenesis and consequently increases the surface area of tumor cells in contact with lymphatic endothelial cells." (PMID 29977159, 2018). "SEMA5A is a novel member of this family and studies on various cancer types have suggested both tumor suppressive and oncogenic roles for SEMA5A." (PMID 30577767, 2018).
tumor (continued). "In contrary to our initial expectations, orthotopic injection of SEMA5A knockdown cells into nude mice resulted in a significant increase in both tumor burden and liver metastases in comparison with the Control cells." (PMID 30577767, 2018). "We also confirmed the maintenance of SEMA5A knockdown in the tumors formed by injection of T3M-4 cells by performing immunohistochemical staining of SEMA5A in tumor sections." (PMID 30577767, 2018). "First, we analyzed the distribution of SEMA5A expression values for both tumor samples and matched controls using box plot analysis to find outliers in the data." (PMID 29464045, 2018). "We observed higher SEMA5A expression in highly metastatic L3.6pl cells derived from liver metastasis than the low metastatic potential L3.3 cells derived from primary tumor." (PMID 29464045, 2018). "An understanding of these mechanistic pathways is required for the potential clinical application of SEMA5A as a molecular marker of tumor metastasis and potential prognostic marker." (PMID 29977159, 2018). "Our previous observations indicate that in the primary tumor setting, SEMA5A promotes proliferation and angiogenesis, thereby enhancing metastasis." (PMID 30577767, 2018). "DFS was significantly (P < 0.001) lesser in patients with high tumor SEMA5A expression levels than for those with low tumor SEMA5A expression levels." (PMID 29977159, 2018). "We removed these outliers for our analysis, performed a paired Student t-test to analyze this data, and observed significantly higher expression (p = 0.004) of SEMA5A in tumor samples in comparison with their matched controls." (PMID 29464045, 2018). "Next, we for the first time analyzed the expression of SEMA5A in the mouse PC progression using KC mice models with tumor sections obtained at different week/time points (10–50 week)." (PMID 29464045, 2018). "We have also demonstrated that SEMA5A has a constitutive expression in PC cell lines derived from metastatic sites in comparison with low endogenous expression in the primary tumor-derived cell line." (PMID 30577767, 2018). "Finally, FAP was associated with ECM and adhesion genes (FN1, COL5A1, SPOCK1, CDH13) and regulators of migration (NREP, SEMA5A), consolidating its central role in matrix deposition and tumor invasion, as previously shown." (PMID 41198614, 2025). "Furthermore, the M2 TAM CM would lose its growth stimulation effects on PANC1 tumor cell once SEMA5A was eliminated via immune precipitation (IP), which have manifested the important roles of SEMA5A in PLXNB3-induced proliferation advantage." (PMID 36741230, 2023). "What is more, the removement of FBS could induce the apoptosis of tumor cells with vehicle or SEMA5A-ΔTSP exposure, while the apoptosis effects were significantly attenuated with treatment of rSEMA5A." (PMID 36741230, 2023). "SEMA5A, but not the truncated protein rSEMA5A-ΔTSP, could induce PKM2 or PGK1 expressions in tumor cells residing in metastatic niches, elucidating the importance of SEMA5A-PLXNB3 axis in the Warburg effect triggering." (PMID 36741230, 2023). "The effects they exert on tumor cells were through secreting SEMA5A." (PMID 36741230, 2023). "We have discovered that M2 type TAM-derived SEMA5A could bind to its tumor cell-expressed receptor PLXNB3 to promote tumor cell proliferation and outgrowth." (PMID 36741230, 2023). "In mechanism investigation, we have discovered that SEMA5A-PLXNB3 axis could achieve tumor cell proliferation and survival via enhancing aerobic glycolysis termed as the Warburg effects." (PMID 36741230, 2023). "Additionally, proliferation and angiogenesis are promoted by SEMA5A in the primary tumor setting, thereby enhancing metastasis." (PMID 36713527, 2022).
tumor (continued). "Furthermore, upregulation of mouse Sema5A in Panc1 enhanced tumor cell proliferation and the incidence of distant metastasis to the lymph nodes, liver, spleen, and peritoneal cavity after in situ injection in mice." (PMID 36713527, 2022). "SEMA5A expression (P = 0.032), tumor grade (P < 0.001), FIGO stage (P < 0.001), LMN (P < 0.001), presence of lymphatic invasion (P < 0.001), VEGF-C expression (P < 0.001), and LMVD (P = 0.005) remained independent prognostic factors for OS in the multivariate analysis." (PMID 29977159, 2018). "In the present study, we tested the hypothesis that knockdown of endogenous SEMA5A expression can modulate tumor growth and metastasis in PC." (PMID 30577767, 2018). "In addition, our data indicate that patients with high tumor SEMA5A expression levels are significantly more likely to develop metastases than those with low tumor SEMA5A expression levels." (PMID 29977159, 2018). "In addition, tumor cells that metastasized to the pelvic/aortic lymph nodes also showed high SEMA5A protein expression." (PMID 29977159, 2018). "In this study, we examined whether constitutive SEMA5A expression in metastatic PC cells regulates tumor growth and metastatic potential." (PMID 30577767, 2018). "Before going ahead for characterization of this change in morphology, we confirmed that our injected T3M-4-shSEMA5A cells maintained SEMA5A knockdown by performing immunohistochemical staining of SEMA5A on tumor sections of mice injected with Control and knockdown cells." (PMID 30577767, 2018). "In this present study, we determined the prospects of SEMA5A as a potential therapeutic target for PC by analyzing the pattern of SEMA5A expression in both human and murine PC tissues of the primary tumor as well as metastasis, and normal pancreas and its functional role in PC." (PMID 29464045, 2018). "This leads to the potential that some of the mutations in MFD-1 may be chemotherapy induced, however the frequency of mutations observed in SEMA5A and ABCB1 in previous studies of chemotherapy naïve OAC point to these mutations being tumour specific." (PMID 27600491, 2016). "Consistent with this is a recent study that reports the presence a novel missense mutation in plexin-B3 in human pancreatic ductal adenocarcinomas, which prevents interaction with its ligand Sema5A, hence impairing their signaling and contributing to tumor progression." (PMID 23050142, 2012). "Therefore, high tumor SEMA5A expression level was a significant predictor of poor prognosis." (PMID 29977159, 2018). "Furthermore, to understand the functionality of SEMA5A, exogenous expression of either full-length mouse membrane-bound Sema5A or an extracellular domain of mouse Sema5A (secretory) in Panc1 cell line resulted in enhanced metastasis of these cells suggesting a tumor-promoting role of SEMA5A in PC." (PMID 30577767, 2018). "Therefore, it is possible that the Sema5A/plexin-B3 signaling pathway may exert tumor promoting and suppressive effects depending on the type of malignancy." (PMID 25780417, 2015). "We also found that PLXNB3, one of the canonical receptors of SEMA5A, was also aberrantly overexpressed on M2 TAM-infiltrated metastatic niche resident tumor cell membranes." (PMID 36741230, 2023). "We generated SEMA5A knockdown in T3M-4 and CD18/HPAF cells and assessed their phenotypes on in vitro motility, tumor growth, and metastatic progression." (PMID 30577767, 2018). "Because the PI3K/AKT signaling pathway has been shown to increase tumor invasion and metastasis by regulating MMP-2 and MMP-9, we investigated the role of this pathway in SEMA5A-induced invasion." (PMID 29977159, 2018). "Therefore, differences in SEMA5A function may be due to differences in tumor biology." (PMID 29977159, 2018). "In the case of VEGFA, SEMA5A, and SEMA3G, the expression levels in the MSL subtype were closer to those of normal tissues than the tumor average." (PMID 23667446, 2013).